IL21 (interleukin 21)
Diseases named in the same sentence as IL21 in open-access papers (continued):
Sharing a sentence is not in itself a finding about the gene and the disease.
Autoimmunity (97 papers, 2007 to 2026). The occurrence of an immune reaction against the organism's own cells or tissues. "The role of the interleukin encoded by the neighboring gene IL2 in autoimmunity seems to be the opposite of that of IL-21." (PMID 39746095, 2025). "In this regard, elevated levels of IL-21 are known to be associated with autoimmunity both in humans and mice." (PMID 38164992, 2024). "Serum levels of IL21 have been proposed as biomarker for the risk of developing secondary autoimmunity following alemtuzumab treatment." (PMID 37533036, 2023). "Among the most highly DE genes and the highest DE cytokine gene was Il21, which encodes IL-21, a pleiotropic cytokine with varied roles in innate and adaptive immunity and implicated in autoimmunity." (PMID 33916486, 2021). "Clough, L.E.; Wang, C.J.; Schmidt, E.M.; Booth, G.; Hou, T.Z.; Ryan, G.A.; Walker, L.S.K. Release from regulatory T cell-mediated suppression during the onset of tissue-specific autoimmunity is associated with elevated IL-21." (PMID 31557991, 2016). "Whereas IL-21 drives autoimmunity by expanding and activating pathogenic T cell subsets, NK cells and promoting antibody production by B cells, it can also inhibit T cell responses following decrease antigen-presenting cells (APC) function." (PMID 27467597, 2016). "In line with these mouse data, in the DC/T-cell co-cultures we observed potent additive effects of IL-7 and TSLP on production of Th17-associated cytokines IL-17, IL-21 and IL-22 that can strongly stimulate autoimmunity." (PMID 26110994, 2015). "In mouse models of SLE and diabetes, increased IL-21 production was shown to be associated with autoimmunity." (PMID 24944624, 2014). "Genetically determined interleukin-21 (IL-21) levels appear to predict partly who is at risk of secondary autoimmunity, an important side effect in a subset of treated patients." (PMID 23730204, 2012). "The dynamic balance between Th17 and Treg cells is essential for maintaining immune homeostasis: Treg cells expressing IL-10 and TGF-β establish pregnancy tolerance, while Th17 cells producing IL-17, IL-21, and IL-22 are associated with pregnancy loss and autoimmunity." (PMID 40894398, 2025). "These varied actions may suggest that IL-21’s role in autoimmunity may depend on the cytokine milieu and IL21R variants." (PMID 40979706, 2025). "Furthermore, our studies revealed a vulnerability in autocrine IL-21 CD4+ T cell signaling as a potential targeted approach to reduce ICI-associated autoimmunity." (PMID 40626363, 2025). "In conclusion, plasma IL-21 levels in adults with established type 1 diabetes were increased, which may be associated with autoimmunity." (PMID 37415982, 2023). "The physiologically higher plasma IL-21 levels in children may, however, mask potential changes caused by T1D autoimmunity." (PMID 37415982, 2023). "IL-21 has been described to stimulate formation of autoimmunity-associated B cells." (PMID 35368991, 2022). "Therefore, IL-21 has been suggested as a potential biomarker for the risk of secondary autoimmunity by Jones and colleagues, however verification in a large prospective cohort is still missing." (PMID 26966029, 2016). "Moreover, elevated serum levels of IL-21 are a biomarker for the risk of developing autoimmunity and the presence of autoantibodies is a recurrent finding in VL patients." (PMID 24763747, 2014). "Although it is unclear whether αζDKO Tfr-cells were impaired in suppressive function, they gained expression of Tfh-associated cytokine Il21 as well as Th2-associated cytokines Il4 and Il13, which might have contributed to the IgG1/IgE-predominant antibodies and autoimmunity in Treg-αζDKO mice." (PMID 39651265, 2025). "Furthermore, a longitudinal study assessing the transition of naïve CD4+ T cells to activated memory autoreactive T cells from the blood of infants found that increases in IL-21 and Tfh gene signatures were associated with later development of β cell autoimmunity in children." (PMID 33262765, 2020).
Autoimmunity (continued). "Another discussed risk factor that may predispose to autoimmunity is an overproduction of IL-21." (PMID 32503344, 2020). "However, all three of IL-2, IL-15 and IL-21 have been implicated in autoimmunity, and using such cytokines to activate endogenous NK cells may favour inflammation and promote autoreactivity." (PMID 18053164, 2007). "Defects in IL-21 signaling have been found to result in impaired dark zone compartments in immunization-induced GC as well as in GC triggered by autoimmunity and viral infection." (PMID 38164992, 2024). "In another study, it was demonstrated that the inappropriate phosphorylation of IRF4 by ROCK2 downregulated production of IL-17 and IL-21 cytokines, which aggravated autoimmunity in mouse models." (PMID 38674328, 2024). "Helper T cells 17 (Th17) are a subpopulation of T cells that are capable of secreting IL-17, IL-21, and IL-22, which mainly play important roles in autoimmunity and defense response against extracellular bacteria or fungi." (PMID 38349411, 2024). "These latest insights into IL-21-dependent modulation of adaptive immunity provide fertile ground for future work aimed at untangling the contribution of exacerbated IL-21 production to the immune dysregulation observed in the context of autoimmunity." (PMID 38164992, 2024). "Upregulation of IL-21 in infiltrating CD4+ T cells and its expression by clonally expanded T cells suggest a critical role for IL-21 signaling in PNS autoimmunity development." (PMID 39087473, 2024). "Cultured NK cells acquired exaggerated cytotoxicity against K562 tumor cells, with development of autoimmunity against healthy MSCs simultaneously in the presence of IL-2 and IL-21." (PMID 38106519, 2023). "A major challenge in deploying IL-21 therapeutically is harnessing its immunostimulatory effects while minimizing off-target autoimmunity." (PMID 37339051, 2023). "We also assayed the effects of TLR7 agonism and IL-21 stimulation of LCLs on cell proliferation and the induction of plasma cells, both of which are characteristics of atMBCs in autoimmunity." (PMID 36248899, 2022). "Intriguingly, Tfh cells and IL-21, both suggested to be downregulated by verapamil, have recently been reported to play an important role in the autoimmunity of T1D12–14." (PMID 35241690, 2022). "Our study can also constitute a starting point for approaching the role of CXCR5+ and IL21+ CD8 T-cells (Tfc) in the context of autoimmunity." (PMID 33603079, 2021). "IL-21 is the most recently discovered common gamma-chain cytokine that promotes persistent T-cell responses in chronic infections, autoimmunity and cancer." (PMID 31756235, 2019). "Spolski, R.; Leonard, W.J. Interleukin-21: Basic biology and implications for cancer and autoimmunity." (PMID 31557991, 2016). "In this regard, an important role of IL-21 (either from TFH or from other cell sources) as a player in the differentiation of Th17 cells that are important in autoimmunity has been recently proposed." (PMID 27069935, 2016). "The first indication of a potential involvement of IL-21 in autoimmunity was the finding that IL-21 was overexpressed in several strains of mice (e.g., BXSB-Yaa, B6.Sle1-Yaa, Sanroque, MRL/MpJ-FASlpr/lpr/J) that develop lupus-like disease." (PMID 24600453, 2014). "IL-21 is in clinical use to promote tumor rejection and is an emerging target for neutralization in the setting of autoimmunity." (PMID 24470500, 2014). "Different studies with animal models have clearly supported the involvement of IL-21 as well as IL2/IL2R pathway as potential drivers of autoimmunity." (PMID 23676143, 2013). "In the BXSB-Yaa mouse model of SLE, serum IL-21 levels increased with age and were correlated with the severity of autoimmunity." (PMID 23638156, 2013). "In numerous murine models of autoimmunity, the inhibition of the function of Tfh cell-associated molecules, such as CD40 L, ICOS, and IL-21, has been shown to result in reduced autoantibody production." (PMID 23861861, 2013).
Autoimmunity (continued). "Our data provides another aspect critical in the regulation of autoimmunity by IL-21, which can negatively impact the size of the lymphoid compartment." (PMID 18773086, 2008). "The role of IL-21 in autoimmunity has been studied extensively." (PMID 39746095, 2025). "Remarkably, 2 CD4+ T cell populations (clusters 2 and 3) significantly upregulated IL-21, a cytokine linked to type 1 diabetes and other autoimmune conditions but not yet to PNS autoimmunity." (PMID 39087473, 2024). "Nevertheless, IL-21 has been shown to support Tfh cell expansion and maintenance and it has a marked impact on the ratio of Tfh to follicular regulatory T cells (Tfr) in transient as well as autoimmune GC." (PMID 38164992, 2024). "Regarding CVID and SIgAD patients, association studies suggest that defective IL-4 and IL-21 signaling has been linked to an increased prevalence of non-infectious complications, including autoimmunity." (PMID 37243231, 2023). "Results indicated that IL-2/IL-15 and IL-2/IL-21 pretreated groups showed significant autoimmunity against MSCs, which are consistent to the expression of activating receptors and intracellular levels of cytotoxic soluble factors (Supplementary 4) in the NK cell culture." (PMID 38106519, 2023). "Given the reported role of IL-21 in autoimmunity, we also assessed whether our IL-21 partial agonists reduced autoantibody production relative to WT." (PMID 37339051, 2023). "The physiologically high plasma IL-21 levels in children may, however, reduce the potential of IL-21 as a biomarker for autoimmunity in pediatric subjects." (PMID 37415982, 2023). "NR4A2 controls IL‐21 secretion by Th cells in a model of organ‐specific autoimmunity." (PMID 36069030, 2022). "Furthermore, intervention of this feedback loop by IL-21 blockade, with IL-21R.Fc administration or IL-21 receptor deletion, attenuated Blimp-1 deficiency–mediated colitis and reinforced the circuit between Blimp-1 and IL-21 in the regulation of autoimmunity." (PMID 35503415, 2022). "Th17 cells are mediators of inflammation and autoimmunity and secrete IL-17, IL-21, and IL-22." (PMID 36012429, 2022). "Furthermore, elevated IL-4/IL-21 serum levels and increased numbers of IL-4/IL-21 producing T cells were observed in several human autoimmune conditions." (PMID 35911775, 2022). "IL21 down regulates FOXP3+ regulatory T cells leading to enhanced autoimmunity." (PMID 32116981, 2019). "The redundancy and possible additive or synergistic effects of the IL-6 and IL-21 pathways, as well as the therapeutic potential of combined pathway blockade in Th17-driven autoimmunity remain unclear." (PMID 28158305, 2017). "Overall, the study of the biological actions and signaling mechanisms of IL-21 has provided critical basic insights and the rationale for clinical evaluation of IL-21, both in cancer and in the use of antibodies to IL-21 in autoimmunity and potentially other diseases as well." (PMID 26966515, 2016). "Finally, we discuss the actions of proinflammatory cytokines that breach immune tolerance and induce autoimmunity, which include IL-7, IL-12, IL-21, and IL-23." (PMID 27574641, 2014). "Early studies showing that two mouse models of SLE have elevated IL-21 levels suggested that IL-21 may play a role in autoimmunity." (PMID 22030011, 2011). "Our previous studies of NOD mice led us to hypothesize that elevated IL-21 levels contribute to the development of disease by creating a lymphopenic environment that drives homeostatic expansion and autoimmunity." (PMID 18773086, 2008). "Therefore, targeting the IL-6/IL-21/SOCS2/STAT5 pathways to restore NK-cell function against autoimmunity may hold therapeutic promise for MG." (PMID 39346912, 2024). "Furthermore, while we have focused on the role of IL-21 within the GC in this review, it has emerged that appropriate regulation of IL-21 production in T cells collaborating with B cells at extrafollicular sites is also crucial for the prevention of autoimmunity." (PMID 38164992, 2024).
Autoimmunity (continued). "Collectively, these findings raise the possibility that the exacerbated IL-21 production that has been widely reported across many autoimmune conditions may contribute to disease development by allowing selection, expansion and differentiation of GC B-cell clones that would otherwise be outcompeted." (PMID 38164992, 2024). "Equally, excessive IL‐21 production could result in the potentially detrimental lowering of BCR or CD40 signaling thresholds and/or exaggerated B cell expansion and thus predispose to autoimmunity." (PMID 35801309, 2022). "IL-21 may drive cycles of T cell expansion and apoptosis to excess increasing the stochastic opportunities for T cells to encounter self-antigen and, hence, lead to autoimmunity." (PMID 32503344, 2020). "Moreover,in vitro expansion of regulatory B10 cells by IL-21 is potent in a mouse model and thus may have potential for human autoimmunity as well, an area for future research." (PMID 26966515, 2016). "Besides, evidence has shown that excessive production of IL-21 led to autoimmunity." (PMID 25889760, 2015). "Earlier evidence of IL-21 (or a combination of IL-21 and IL-7) as a potential biomarker has not been substantiated in larger prospective cohorts, further complicated by the inability of currently available IL-21 ELISA kits to predict autoimmunity after alemtuzumab." (PMID 26204829, 2015). "In summary, our data identify a role for IL-21+IFN-γ+ Tfh cells in ICI-T1DM and demonstrate that inhibition of these 2 cytokine pathways can prevent the development of autoimmunity." (PMID 40626363, 2025). "Th17 cells, a subpopulation of CD4+ T cells, are involved in coordinating host defense and inflammatory responses in autoimmunity, with BATF binding to the promoters of genes related to Th17 differentiation, including IL-17, IL-21, and IL-22." (PMID 38786064, 2024). "Moreover, the analysis of patients with type 2 diabetes could help confirm whether the increased plasma IL-21 levels in adults with T1D are truly associated with autoimmunity and are not secondary to hyperglycemia and/or exogenous insulin use." (PMID 37415982, 2023). "B-cells can also cause cell death or, in the form of regulatory B10 cells, can induce autoimmunity if they receive a strong signal via BCR, or via TLR, and IL-21 costimulation." (PMID 27602031, 2016). "Elevated frequencies of IL-21-compent CD8+ T cells have been described in HIV-1 infection and autoimmunity." (PMID 26785168, 2016). "Thus, our data expanded the prevailing belief that Tfh cells only augment autoimmunity and demonstrated that Tfh cells may function to maintain immune homeostasis by expanding the regulatory B-cell pool and stimulating IL-10 production via induction of IL-21." (PMID 23638156, 2013). "Furthermore, our data suggest IL-21 may contribute to the development of autoimmunity." (PMID 18773086, 2008). "One explanation would be the lack of an inflammatory milieu with IL-21, TGFβ, or IL-23, which is known to induce the production of Th17 cytokines and promote autoimmunity in the presence of a cognate antigen, driving their maturation and maintenance." (PMID 40150012, 2025). "Of note, patients with autism have increased inflammatory cytokines IL-21, IL-22, IFN-γ, and IL-4 from T cells, decreased antiinflammatory cytokines TGFβ and IL-10, two functional cytokines produced by Tregs, activated T cells, and/or autoimmunity." (PMID 40155813, 2025). "Inhibition of IL-6/IL-21/SOCS2/STAT5 pathway and recovery of NK-cell ability to inhibit autoimmunity may be a new direction in the treatment of MG." (PMID 39346912, 2024). "Secondly, patients with MS who developed autoimmunity upon alemtuzumab showed more than twofold higher serum interleukin-21 levels compared to patients with no autoimmunity." (PMID 32708663, 2020).
Autoimmunity (continued). "Based on these findings, we propose that while Act1 is a necessary signaling molecule for IL-17 signaling, Act1 serves as a negative regulator to modulate Th17-B cell interaction via its impact on IL-23/IL-21/STAT3 axis and CD40, thereby controlling autoimmunity." (PMID 30013031, 2018). "We aimed to investigate for the first time the potential influence of the IL2/IL21, IL2RA and IL2RB most associated polymorphisms with autoimmunity on the endogenous non-anterior uveitis genetic predisposition." (PMID 23676143, 2013). "It has been demonstrated that IL-21-producing Th-cells induce Th17 development and proliferation, which has been shown to promote germinal center (GC) formation in a BXD2 mouse model of autoimmunity." (PMID 23799890, 2013). "Finally, NKG2D, a powerful activating receptor involved in the regulation of immune responses during infection, cancer and autoimmunity, was preferentially detected on CD34-lineage- cells cultured with IL-15 and IL-21." (PMID 19712464, 2009). "To investigate the mechanism whereby IL-21 affects the immune system, we investigated its role in T cell homeostasis and autoimmunity in both non-autoimmune C57BL/6 and autoimmune NOD mice." (PMID 18773086, 2008). "The same analysis was performed on the patient who developed secondary autoimmunity; a significant increase in the mRNA levels of IL-21 was detected at baseline in the subject who developed thyroiditis compared with subjects who did not develop secondary autoimmunity." (PMID 35296069, 2022). "The first revealed that serum IL-21 was at least 2-fold higher in a cohort of 32 patients who developed autoimmunity compared with 27 patients who did not, a phenomenon that may reflect a genetic predisposition." (PMID 32539719, 2020). "IL-21 affects the differentiation and proliferation of NK cells together with IL-2 and IL-15, and is involved in the differentiation of T-helper 17 (Th17) cells, a recently identified subset of CD4+ T cells that produce IL-17A, IL-17F and IL-22 and promote inflammatory and autoimmune conditions." (PMID 19712464, 2009). "Due to their presence also in non-lymphoid organs and their IL-21 and IFN-γ co-expression, the super-functional cell subset might be superior in activation-induced processes that drive autoimmunity by expanding pathogenic T cell subsets in non-lymphoid tissue and promoting inflammation." (PMID 32441253, 2020). "On the other hand, IL-21 influences B-cell function: IL-21 signaling in B cells is required, together with CD4− T cell cooperation, for their differentiation to antibody-producing plasma cells, that in turn could be important in the development of antibody-induced autoimmunity." (PMID 32503344, 2020). "Hence, inhibition of IL-21 may be better suited in preventing the transition from autoimmunity to inflammation rather than inhibiting the effector phase of the disease." (PMID 32332730, 2020). "The lack of a significant difference in IL-21 levels between T1DM patients and the healthy controls is somewhat surprising, given the known role of IL-21 in promoting T cell-mediated autoimmunity." (PMID 39211721, 2024).